CTCFL (CCCTC-binding factor like)
Diseases named in the same sentence as CTCFL in open-access papers (continued):
Sharing a sentence is not in itself a finding about the gene and the disease.
tumor (42 papers, 2008 to 2025). "First, tumor recognition was assessed using a panel of naturally expressing PRAME or CTCFL positive tumor cell lines, all expressing the target HLA allele." (PMID 37026005, 2023). "The excluded T-cell clones exhibited either limited recognition of PRAME or CTCFL positive OVCA/tumor cell lines (25/56), or were cross-reactive against peptides in commonly expressed HLA alleles (27/56)." (PMID 37026005, 2023). "In other tumor types CTCFL expression has also been detected, although expression data have been contradictory." (PMID 37026005, 2023). "In line with the upregulation, recognition of DAC-treated OVCA tumor cell lines COV413b and A2780 was significantly increased for CTCFL TCR-T cells." (PMID 37026005, 2023). "Although CTCFL has been proposed as an attractive tumor target given the restricted expression profile and several oncogenic properties, studies investigating CTCFL-targeting therapies are still limited." (PMID 37026005, 2023). "CTCFL (BORIS) is a pivotal DNA binding protein involved in tumor regulation, and it also serves as a vital immunotherapeutic target." (PMID 34721660, 2021). "Given that CTCFL (BORIS) has been found to be mainly deregulated in OC samples compared with other types of neoplasms, the aim of our study was to explore the participation of BORIS in gene regulation in OC." (PMID 31406110, 2019). "These T-cell clones effectively recognized all PRAME or CTCFL positive OVCA/tumor cell lines." (PMID 37026005, 2023). "Second, cross-reactivity with other peptides presented in the target HLA allele was assessed using a panel of PRAME or CTCFL negative tumor cell lines and healthy cell subsets." (PMID 37026005, 2023). "Furthermore, Stat1, a protein with both tumor suppressor and oncogenic properties was bound and activated by CTCFL." (PMID 32393311, 2020). "Molecular lesions of CTCFL gene were observed in less than 10% of common tumours examined." (PMID 30275357, 2018). "Since CTCFL expression is epigenetically regulated and treatment with demethylating agent DAC has previously been shown to upregulate expression of CTCFL in OVCA tumor cell lines, we investigated whether DAC can make tumor cell-lines more susceptible to CTCFL-mediated killing." (PMID 37026005, 2023). "Bioinformatics analysis revealed that CTCFL and DPPA2 were both upregulated in tumor tissues relative to the normal tissues in the TCGA-STAD dataset." (PMID 34721660, 2021). "CTCFL, also known as BORIS, is a transcriptional regulator; it directs epigenetic reprogramming at CTCF target sites in normal and tumor tissues." (PMID 23592437, 2013). "In order to enlarge the dataset, various tumor cell lines and primary AML patient samples expressing the selected genes were additionally included, some of these cell lines were transduced with CTCFL, CLDN6 and/or HLA class I molecules." (PMID 37026005, 2023). "CTCFL, the paralogous factor of CTCF, is expressed in germ cells and in some tumour types." (PMID 25294833, 2014). "CTCFL upregulation by DAC was restricted to tumor cells, as DAC treatment of healthy fibroblasts did not upregulate CTCFL expression and did not induce recognition by CTCFL TCR-T cells." (PMID 37026005, 2023). "Despite high CTCFL expression in primary OVCA patient samples, OVCA tumor cell lines did not express CTCFL." (PMID 37026005, 2023).
infection (2 papers, 2021 to 2025). The state of being infected such as from the introduction of a foreign agent such as serum, vaccine, antigenic substance or organism. "Footprint analysis of ATAC peaks also revealed slight increases in signals for CTCF and CTCFL transcription factors following infection." (PMID 40539063, 2025). "CTCFL, the gene encoding the CTCF-homolog BORIS, is also significantly increased over the course of infection, while CTCF itself remains stable." (PMID 33497421, 2021).
CTCFL also shares sentences with these, for which no sentence is quoted: lung carcinoma (8 papers); breast tumors (5); chronic myelogenous leukemia (4); esophageal cancer (4); glioblastoma (4); head and neck squamous cell carcinoma (3); neuroblastoma (3); cancer testis (2); colorectal cancer (2); hepatocellular carcinoma (2); non-small cell lung carcinoma (2); uterine corpus cancer (2); uterine tumor (2); and-neck cancer (1); cardiovascular diseases (1); colorectal adenocarcinoma (1); diffuse astrocytoma (1); embryonal carcinoma (1); endometrioid tumor (1); estrogen-receptor negative breast cancer (1); influenza (1); invasive breast carcinoma (1); invasive ductal carcinomas (1); invasive lobular carcinomas (1); laryngeal squamous cell carcinoma (1); leukemia (1); lymph node metastasis (1); metastatic diseases (1); metastatic melanoma (1); mucinous carcinomas (1).
A further 20 diseases each share a sentence with CTCFL in 1 paper.